MDM2 (MDM2 proto-oncogene)
Diseases named in the same sentence as MDM2 in open-access papers (continued):
Sharing a sentence is not in itself a finding about the gene and the disease.
tumor (continued). "CircRNA hsa_circ_0002874 acts as a sponge for miR1273f and thereby affects the level of MDM2, eventually acting as a tumor promoter in NSCLC." (PMID 33612481, 2021). "Note that Mdm2 inhibitors are in a class of molecules currently being evaluated in clinical trials for tumor therapy." (PMID 33563973, 2021). "have previously shown the presence of MDM2 DNA in EVs isolated both from the tumor and from the patient circulation." (PMID 33643547, 2021). "The purpose of the current study was to investigate the ability of ibrutinib plus the MDM2-inhibitor nutlin-3 to counteract the tumor microenvironment protective effect." (PMID 34287267, 2021). "In Osa, overexpression of PCAT6 enhances cell proliferation, migration, and invasion in vitro, and tumor growth in vivo, while depression of MDM2 proto-oncogene (MDM2) exerts an opposite influence." (PMID 34885209, 2021). "We also demonstrated anti-tumor effects by the combination of Ad-delE1B and the MDM2 inhibitors in an orthotopic animal model." (PMID 34230456, 2021). "From these, a fluoroethoxy analogue of SP-141 was labeled with 18F and evaluated for its uptake in MDM2 expressing tumor cell lines in vitro." (PMID 33924734, 2021). "Meanwhile, the results of WB and immunohistochemistry showed that hsa_circ_0000073 silencing markedly reduced the expression of CCNE2 or MDM2 in tumor tissues." (PMID 34568326, 2021).
tumor (continued). "All these results insinuated that depletion of HCG11 suppressed the tumor growth by targeting miR-579-3p/MDM2, thereby inhibiting tumor cells proliferation, promoting tumor cells apoptosis and blocking tumor cells movement." (PMID 34230221, 2021). "Herein we investigate the feasibility of developing 18F-labeled compounds based on the small molecule inhibitor SP-141 for imaging tumor MDM2 expression levels with positron emission tomography (PET)." (PMID 33924734, 2021). "Here we show that a single dose of MDM2 inhibitor delivered shortly after radiation treatment of a tumor results in improved tumor control." (PMID 33563973, 2021). "The data obtained showed that MDM-2 gene expression in both tumor cell lines was influenced in a different way." (PMID 34204834, 2021). "Comparative analysis of CisPt or the effects induced by RSV applied separately versus CisPt + RSV combination therapy showed that RSV was responsible for modulating MDM-2 gene expression in PE/CA-PJ49 tumor cells." (PMID 34204834, 2021). "With respect to CFA10, Mdm2 is recurrently amplified, with a fourfold enhancement of transcripts across a cohort of 39 oral melanoma tumours compared with adjacent normal tissue, and up to 19-fold enhancement for individual tumours harbouring the CNA." (PMID 34822659, 2021). "Recently, several studies have revealed that lncRNAs can regulate the proliferation, migration, and invasion of multiple types of malignant tumor cells by influencing murine double minute 2 (MDM2) expression." (PMID 33809929, 2021).
tumor (continued). "Considering its strong tumor-enhancing properties, MDM2 has become an attractive potential therapeutic target." (PMID 34072462, 2021). "On the contrary, a tumor-suppressive function is proposed by the inhibition of proliferation (via MDM2), immunosuppression (via TGFβ), as well as angiogenesis and fibrosis (via CTGF)." (PMID 33803955, 2021). "This role of Mdm2 would be consistent with suggested tumor suppressor functions proposed for this ligase in the appropriate context." (PMID 33806062, 2021). "M60 tumor exhibited two chromosome 12 loci resulting in high gene overexpression, including of MDM2, YEATS4 and FRS2." (PMID 33853673, 2021). "The majority of MDM2 amplifications were observed in post-treatment samples, suggesting that tumour cells are selected during treatment." (PMID 34281219, 2021).
tumor (continued). "Nutlin-3 was the first developed small molecule effective in antagonizing MDM2 activity and counteracting tumor growth." (PMID 34072462, 2021). "More recently, a body of natural products, ranging from flavonoids, steroids and sesquiterpenes to alkaloids, have been explored as MDM2 inhibitors and shown to exhibited anti-tumor effects." (PMID 33670160, 2021). "HDAC2 was highly co-expressed with MDM2, and pharmacological HDAC2 inhibition decreased MDM2 expression and enhanced tumor cell apoptosis." (PMID 35008848, 2021). "Studies suggest that SP-141 directly binds to the MDM2 protein and decreases its expression levels in tumor cells by promoting autoubiquitination and proteasomal degradation of MDM2." (PMID 33924734, 2021). "MDM2 inhibitors, for instance, have been shown to enhance tumor immunity and synergize with the PD-1/PD-L1 immune-checkpoint blockade." (PMID 34572908, 2021).
tumor (continued). "Consistent with our observation of changes in PD-L1 with MDM2 blockade, a recent study using another MDM2 inhibitor APG-115 resulted in increased surface expression of PD-L1 on tumor cells." (PMID 32655895, 2020). "These synthetic compounds showed excellent targeted inhibitory effects on HDAC and MDM2 in analysis of biochemical evaluation and structure-activity relationship as well as good anti-tumor activity in the xenograft model of A549 in vivo." (PMID 32477121, 2020). "In a molecular profiling study of 102,878 patients, this same group identified the amplification of MDM2 in 3.5%, with large variations among tumor types (63.6% in liposarcoma and <1% in thyroid carcinoma and adenocarcinoma of colon and rectum)." (PMID 32265935, 2020). "In this study, MDM2 amplification was found in the primary tumor tissue of a single case of GC (2.70%)." (PMID 31454863, 2020). "The immunohistochemical analyses performed on the tumor of the first case were positive for MDM2 and CDK4." (PMID 31282548, 2020). "MDM2 is a caspase-2 substrate that has the potential to reveal the mechanism of tumor suppression by caspase-2 due to its own ability to regulate both apoptosis and cell cycle." (PMID 33425918, 2020).